TUSC1 (tumor suppressor candidate 1)
Synonyms: TSG9; TSG-9; CCDC89B
Tractability: PROTAC: its protein half-life has been measured.
Gene: Protein-coding gene on chromosome 9 (25,676,969 to 25,678,444, reverse strand). Ensembl gene ENSG00000198680.
Subcellular location (Human Protein Atlas): Vesicles; Nucleoplasm
Genetic constraint (gnomAD): Loss-of-function variants: 12 observed, 5.51 expected, observed/expected ratio (o/e) 2.18. That is too few expected variants to judge how well the gene tolerates losing a copy. Missense variants: 442 observed, 227.47 expected, observed/expected ratio (o/e) 1.94, 90% interval 1.78 to 1.99. Synonymous variants: 192 observed, 97.12 expected, observed/expected ratio (o/e) 1.98, 90% interval 1.72 to 1.99.
Homologues: Orthologues: chimpanzee TUSC1 (98% identical), macaque TUSC1 (87% identical), dog TUSC1 (80% identical), pig TUSC1 (77% identical), rabbit TUSC1 (77% identical), mouse Tusc1 (73% identical), rat Tusc1 (72% identical).
Diseases named in the same sentence as TUSC1 in open-access papers:
TUSC1 is named in the same sentence as 14 diseases in open-access papers, as found by Europe PMC text mining. Sharing a sentence is not in itself a finding about the gene and the disease. The quoted sentences say what the papers report.
glioma (4 papers, 2020 to 2024). A benign or malignant brain and spinal cord tumor that arises from glial cells (astrocytes, oligodendrocytes, ependymal cells). "Previous research has indicated that the TUSC1 gene is under-expressed in many human tumors such as gliomas and CRC." (PMID 39044262, 2024). "Furthermore, amplification peaks of oncogenes (PIK3C2B, PDGFRA, EGFR, CDK4), and deletion peaks of tumor suppressor genes (TUSC1, CDKN2A, CDKN2B, PTEN, FAS, BNIP3) were detected in the gliomas with a high risk score." (PMID 32023222, 2020). "Also, the novel lncRNA MIR497HG considered new tumor suppressors and prognostic biomarkers in glioma and significantly inhibited glioma cell proliferation ability and cell cycle progression via targeting CCNE1 and the miR-588/TUSC1 axis." (PMID 35795204, 2022).
lung cancer (4 papers, 2013 to 2022). A malignant neoplasm involving the lung. "The data also showed a trend towards increased survival times for lung cancer patients with higher levels of TUSC1 expression." (PMID 23776618, 2013). "Taken together, we have provided further evidence that TUSC1 expression is downregulated in lung cancer cell lines and a trend towards higher expression of TUSC1 is correlated with longer survival times for lung cancer patients." (PMID 23776618, 2013). "We had previously reported a putative tumor suppressor gene, TUSC1, which resides in a region of homozygous deletion at marker D9S126 and we had demonstrated reduced expression of TUSC1 mRNA in human lung cancer cell lines." (PMID 23776618, 2013). "In this study, we examine the differential expression of TUSC1 in human lung cancer cell lines by western blot and in a primary human lung cancer tissue microarray by immunohistochemical analysis." (PMID 23776618, 2013). "Restoration of TUSC1 expression in lung cancer cells is followed by the suppression of tumorigenicity in vivo and slows cell growth in vitro, suggesting TUSC1 functions as a tumor suppressor gene." (PMID 23776618, 2013). "The mechanism by which TUSC1 expression is reduced in lung cancer cells and tumor tissues, and the mechanism by which TUSC1 governs the inhibition of NSCLC cell growth remain to be fully elucidated." (PMID 23776618, 2013). "In the current study, we were able to show reduced and differential expression of TUSC1 protein in lung cancer cell lines and primary lung cancer tissue samples using a TUSC1 specific polyclonal antibody." (PMID 23776618, 2013). "Our previous results located the TUSC1 gene in a homozygous deletion region on chromosome 9p and demonstrated reduced expression in lung cancer cell lines." (PMID 23776618, 2013). "We also examined the correlation between expression of TUSC1 and survival times of lung cancer patients by immunohistochemical analysis of a human lung cancer tissue microarray." (PMID 23776618, 2013). "According to the GeneCards database, tumor suppressor candidate gene 1 (TUSC1) is located on chromosome 9p and is downregulated in non–small cell lung cancer and small cell lung cancer cell lines, suggesting that it may play a role in lung tumorigenesis." (PMID 35846146, 2022). "TUSC1 tumor suppressor candidate 1 (TUSC1) is a putative tumor suppressor gene and could restrain lung cancer and glioblastoma cells growth in vitro." (PMID 33682883, 2021). "Moreover, our data indicate higher levels of TUSC1 expression is correlated with increased survival times for lung cancer patients." (PMID 23776618, 2013). "Interestingly, the results from a primary human lung cancer tissue microarray suggested that higher expression of TUSC1 was correlated with increased survival times for lung cancer patients." (PMID 23776618, 2013). "We previously reported the identification of TUSC1 (Tumor Suppressor Candidate 1), as a novel intronless gene isolated from a region of homozygous deletion at D9S126 on chromosome 9p in human lung cancer." (PMID 23776618, 2013). "The results showed exogenous and endogenous TUSC1 proteins are located in both the cytoplasm and nucleus of CHO transfected cells as well as in untransfected 9HTE cells and a lung cancer cell line (SKMES-1) endogenously expressing TUSC1." (PMID 23776618, 2013). "In addition, results from confocal microscopy and immunohistochemical analyses show distribution of TUSC1 in the cytoplasm and nucleus in tumor cell lines and in normal and tumor cells in the lung cancer tissue microarray." (PMID 23776618, 2013).
melanoma (3 papers, 2013 to 2023). A malignant, usually aggressive tumor composed of atypical, neoplastic melanocytes. "We then tested the impact of these dCas9-VprBP fusions on the transcription of INPP5J, ZNF750, and TUSC1 genes in G361 melanoma cells." (PMID 37293029, 2023). "Among most significantly altered genes, we selected INPP5J, ZNF750, and TUSC1 for further study because their gene products are known to reduce the viability and malignant proliferation of melanoma cells." (PMID 37293029, 2023). "Among the most significantly altered genes, we selected INPP5J, ZNF750, and TUSC1 for further study because their gene products are known to reduce the viability and malignant proliferation of melanoma cells." (PMID 37760992, 2023). "Also supportive of the idea that VprBP modulates transcription at the level of initiation, dCAS9-VprBP was highly efficient in suppressing the transcription of INPP5J, ZNF750, and TUSC1 genes when guided to their promoter regions by sgRNAs in VprBP-depleted melanoma cells." (PMID 37293029, 2023).
hepatocellular carcinoma (2 papers, 2022 to 2024). A malignant tumor that arises from hepatocytes. "The last core gene, TUSC1, has good clinical predictive value in gastric cancer and hepatocellular carcinoma, and has been reported to inhibit the proliferative ability of tumor cells 57-59." (PMID 35370464, 2022). "In hepatocellular carcinoma (HCC), high methylation within the gene has been identified as a mechanism suppressing TUSC1 transcription." (PMID 39044262, 2024).
bladder cancer (1 paper, 2022). "The hub genes of PPI network also indicated broad correlations between GXYLT2 and bladder cancer progression (such as cancer suppressor gene RPA2 and TUSC1." (PMID 36263004, 2022).
leukemia (1 paper, 2023). A malignant (clonal) hematologic disorder, involving hematopoietic stem cells and characterized by the presence of primitive or atypical myeloid or lymphoid cells in the bone marrow and the blood. "In the current study, we first utilized bioinformatics analysis to ascertain the dysregulated genes associated with autophagy in NPM1-mutated leukemia and obtained three genes including TUSC1, NKX2-3, and TP53INP2." (PMID 36675134, 2023).
tumor (9 papers, 2013 to 2025). "Subsequent clinical analysis revealed associations between TUSC1 expression and tumor size, T-stage, N-stage, and nerve invasion." (PMID 39044262, 2024). "Tumor suppressor candidate 1 (TUSC1) is a tumor suppressor gene that reduces tumor cell growth in vitro and tumor growth in vivo." (PMID 40503228, 2025). "Animal experiments further supported the findings, showing that aberrant TUSC1 expression affected EJC tumor growth and metastasis." (PMID 39044262, 2024). "These research findings indicated that upregulation of TUSC1 in vivo can hinder EJC tumor growth and metastasis." (PMID 39044262, 2024). "In this study, we initially reported the downregulation of TUSC1 in EJC and demonstrated that elevated TUSC1 expression affected tumor cell proliferation, migration, invasion, cell cycle, and apoptosis." (PMID 39044262, 2024). "Animal experiments demonstrated that TUSC1 overexpression inhibited EJC tumor growth and metastasis in vivo." (PMID 39044262, 2024). "Future studies using TUSC1 knock-out mice and identification of its interacting partner(s) and functional pathway(s) will address TUSC1’s physiological roles in tumor development." (PMID 23776618, 2013). "Taken together, our results support TUSC1 has tumor suppressor activity as a candidate tumor suppressor gene located on chromosome 9p." (PMID 23776618, 2013). "We were able to demonstrate localization of TUSC1 protein in both the cytoplasm and nucleus in transfected cells, untransfected cells and primary tumor tissue." (PMID 23776618, 2013). "The results showed a significant downregulation of TUSC1 expression in tumor tissues." (PMID 39044262, 2024). "The role of TUSC1 in tumor occurrence in vivo was examined using a xenograft mouse model." (PMID 39044262, 2024). "The results show that TUSC1 significantly suppresses tumor growth (p<0.05)." (PMID 23776618, 2013). "Taken together, we provide evidence that TUSC1 functions as a tumor suppressor gene in tumor development and TUSC1 may be a potential biomarker for diagnosis, prognosis and treatment." (PMID 23776618, 2013). "Most importantly, introducing the TUSC1 gene into tumor cell lines harboring a homozygous deletion of TUSC1 (Nu6-1 and H290) had the effect of inhibiting cell proliferation in vitro and reducing tumor growth in vivo." (PMID 23776618, 2013). "We further determined whether the inhibitory effects of the TUSC1 gene on tumor cell proliferation in vitro could be demonstrated through tumor growth in vivo in nude mice." (PMID 23776618, 2013). "In addition, we also demonstrated TUSC1 resides in both the cytoplasm and nucleus of normal cells, tumor cell lines and tumor tissue microarrays suggesting TUSC1 may participate in multiple functional pathways for its physiological function." (PMID 23776618, 2013). "Subsequently, we examined TUSC1 expression and the expression of proliferation, EMT, and apoptosis marker proteins in the tumor tissues of various groups using qRT-PCR, WB, and IHC, respectively." (PMID 39044262, 2024). "Subsequently, MSP assays were conducted to evaluate TUSC1 methylation levels in various samples, including 10 pairs of normal and patient tissues, as well as GES-1 and tumor cells." (PMID 39044262, 2024). "The top identified variable TUSC1 is a putative tumor suppressor gene with no previously identified relationship to BOLD-100 response, and follow-up experiments are needed to elucidate the impact of this relationship." (PMID 36612025, 2022). "Moreover, several tumor suppressors, including BTG2, TUSC1, BAK1, LATS2, FZD6 and PPP2R1B, were regarded as common targets of TET3." (PMID 32209730, 2020). "Furthermore, we identified tumour suppressors, including BTG2, TUSC1, BAK1, LATS2, FZD6 and PPP2R1B, as common targets of TLX and TET3." (PMID 26838672, 2016). "The results showed no expression of TUSC1 in TUSC1 homozygously deleted cells and diminished expression in some tumor cell lines without TUSC1 deletion." (PMID 23776618, 2013).
tumor (continued). "In addition, previous studies lacked sufficient functional analysis of TUSC1, and the mechanism of TUSC1 promoter methylation in EJC affecting tumor progression has not been elucidated." (PMID 39044262, 2024). "Additionally, we noted a significant reduction in tumor frequency and volume in the animals subcutaneously injected with TUSC1 stably transfected Nu6-1 cells as opposed to H290 cells and restoration of TUSC1 expression appears to have more effects in vivo than in vitro." (PMID 23776618, 2013).
cancer (5 papers, 2013 to 2024). A tumor composed of atypical neoplastic, often pleomorphic cells that invade other tissues. "For instance, in GC, decreased TUSC1 mRNA expression is implicated in poor prognosis of patients, and TUSC1 is typically suppressed in cancer cells due to high levels of gene methylation." (PMID 39044262, 2024). "Future studies to elucidate the effect of nonsynonymous SNPs will be interesting to understand if there is a cancer-associated SNP(s) and their effects on TUSC1 activity." (PMID 23776618, 2013). "TUSC1 is a recently identified tumor suppressor gene known for its involvement in various types of cancer." (PMID 39044262, 2024). "The results revealed that TUSC1 exhibited significantly lower methylation levels in adjacent tissues compared to EJC tissues, while HGC-27, AGS, and NCI-N87 cancer cells exhibited significantly higher methylation levels than GES-1 normal cells." (PMID 39044262, 2024).
TUSC1 also shares sentences with these, for which no sentence is quoted: gastric cancer (1 paper); glioblastoma (1); Infertility (1); male infertility (1); small cell lung carcinoma (1); spermatogenic failure (1).